CDCA7 (cell division cycle associated 7)
Description:
Participates in MYC-mediated cell transformation and apoptosis; induces anchorage-independent growth and clonogenicity in lymphoblastoid cells. Insufficient to induce tumorigenicity when overexpressed but contributes to MYC-mediated tumorigenesis. Also functions as a critical cofactor for the chromatin remodeler HELLS, facilitating its recruitment to specific genomic regions to maintain DNA methylation patterns and heterochromatin integrity. Recognizes hemimethylated CpG within nucleosomes where it recruits HELLS to remodel chromatin and facilitate access of de novo DNA methyltransferases to heterochromatic regions, enabling proper establishment of DNA methylation patterns. May play a role as transcriptional regulator.
Synonyms: JPO1; FLJ14736; ICF3
Tractability: PROTAC: UniProt records ubiquitination sites on it; ubiquitination databases record sites on it.
Gene: Protein-coding gene on chromosome 2 (173,354,820 to 173,368,997, forward strand). Ensembl gene ENSG00000144354.
Subcellular location: Nucleus; Cytoplasm; Chromosome
Subcellular location (Human Protein Atlas): Cytosol; Nucleoplasm
Gene Ontology:
Molecular function: hemi-methylated DNA-binding; protein binding
Biological process: regulation of cell population proliferation; regulation of DNA-templated transcription
Cellular component: chromosome; cytoplasm; cytosol; nucleoplasm; nucleus
Genetic constraint (gnomAD): Loss-of-function variants: 26 observed, 53.36 expected, observed/expected ratio (o/e) 0.49, 90% interval 0.36 to 0.68. The upper end of that interval is the gene's LOEUF score, 0.68, which puts it in group 2 of 6, group 1 being the genes least tolerant of losing a copy. Missense variants: 484 observed, 605.95 expected, observed/expected ratio (o/e) 0.8, 90% interval 0.74 to 0.86. Synonymous variants: 180 observed, 215.97 expected, observed/expected ratio (o/e) 0.83, 90% interval 0.74 to 0.94.
Gene-disease validity (ClinGen):
ClinGen rates the evidence that CDCA7 causes each of these diseases.
immunodeficiency-centromeric instability-facial anomalies syndrome 3 (autosomal recessive): Moderate.
Homologues: Orthologues: chimpanzee CDCA7 (99% identical), macaque CDCA7 (98% identical), dog CDCA7 (90% identical), pig CDCA7 (90% identical), rabbit CDCA7 (89% identical), mouse Cdca7 (70% identical), rat Cdca7 (70% identical), guinea pig CDCA7 (69% identical), tropical clawed frog cdca7 (54% identical), zebrafish cdca7a (50% identical). Paralogues in human: CDCA7L (39% identical).
Diseases named in the same sentence as CDCA7 in open-access papers:
CDCA7 is named in the same sentence as 56 diseases in open-access papers, as found by Europe PMC text mining. Sharing a sentence is not in itself a finding about the gene and the disease. The quoted sentences say what the papers report.
ICF syndrome (17 papers, 2018 to 2025). "This process is crucial for genome stability, and its disruption can cause ICF syndrome, a disorder associated with mutations in CDCA7." (PMID 41370347, 2025). "When mutated in humans, HELLS also causes ICF syndrome, and patients with CDCA7 and HELLS ICF show overlapping DNA methylation defects in the blood." (PMID 38335290, 2024). "Mutations in both HELLS and CDCA7 have been found to disrupt normal DNA methylation patterns, which cause the progression of ICF syndrome." (PMID 39376563, 2024). "Mutations in CDCA7 have been shown to cause ICF syndrome, a rare primary immunodeficiency characterized by epigenetic abnormalities." (PMID 32859263, 2020). "Since ICF syndrome-associated CDCA7 mutations cause DNA hypomethylation at human centromere alpha-satellite repeats, we hypothesized that Arabidopsis CDCA7α and CDCA7β might similarly regulate repetitive regions, including centromeric CEN178 satellite repeats." (PMID 41370347, 2025). "Recessive mutations in CDCA7 or DNMT3B can cause ICF syndrome." (PMID 38335290, 2024). "In this study, we generated mice carrying an ICF syndrome causing CDCA7 missense variant and used the Cdca7G305V mouse model as a tool to comprehensively investigate the epigenetic and transcriptional consequences of CDCA7 disruption in vivo." (PMID 38335290, 2024). "Mutations in the zf-4CXXC_R1 domain, or HELLS-interacting domain, of CDCA7 lead to DNA hypomethylation at juxta-centromeric satellite DNA, resulting in centromere instability and ICF syndrome." (PMID 41370347, 2025). "Mutations in three critical amino acids (R274, G294, and R304) of the CDCA7 zf-CXXC_R1 domain reduce its binding affinity to hemimethylated CpG sites, leading to ICF syndrome." (PMID 41370347, 2025). "In summary, mutations in DNMT3b, ZBTB24, CDCA7, and HELLS disturb the normal process of DNA methylation, which is critical to the pathogenesis of ICF syndrome." (PMID 39376563, 2024). "Mutations in HELLS, its activator CDCA7, and the de novo DNA methyltransferase DNMT3B, cause immunodeficiency-centromeric instability-facial anomalies (ICF) syndrome, a genetic disorder associated with the loss of DNA methylation." (PMID 37769127, 2023). "The CDCA7/HELLS chromatin remodeling complex, which is mutated in ICF syndrome, contributes to centromeric/pericentromeric stability plausibly by facilitating the replication‐uncoupled process." (PMID 33960584, 2021). "ICF syndrome patients can be classified based on the impaired gene, in addition to DNMT3B (ICF1): ZBTB24 (zinc-finger and BTB domain-containing 24, ICF2), CDCA7 (cell division cycle-associated 7, ICF3), and HELLS (helicase, lymphoid-specific, ICF4)." (PMID 31963661, 2020). "Three other genes are currently known to cause ICF syndrome upon mutation, among them DNA methyltransferase 3B (DNMT3B) (ICF1), mutations in zinc finger and BTB domain containing 24 (ZBTB24) (ICF2), and cell division cycle associated 7 gene (CDCA7) (ICF3)." (PMID 32727902, 2020). "Pathogenic variants in four genes have been shown to cause ICF syndrome: DNMT3B (ICF1), ZBTB24 (ICF2), CDCA7 (ICF3), and HELLS (ICF4)." (PMID 31066130, 2019). "Mutations in lymphoid-specific helicase (HELLS) and cell division cycle associated 7 (CDCA7) can cause a genetically heterogeneous autosomal recessive disorder referred to as centromeric instability and facial anomalies (ICF) syndrome, which is characterized by life-threatening immunodeficiency." (PMID 36032672, 2022). "After the identification of CDCA7 and HELLS in 2015 as causative genes of ICF syndrome, the outline of the molecular pathogenesis regarding the chromosome instability observed in this syndrome has been largely unveiled, although further detailed studies are required." (PMID 33960584, 2021). "A striking example was the discovery of mutations in factors of unknown function but devoid of DNMT activity, namely ZBTB24, CDCA7 and HELLS, as genetic causes of the ICF syndrome." (PMID 33916664, 2021).
ICF syndrome (continued). "Pathogenic variants in four genes have been identified to cause ICF syndrome: DNA methyltransferase 3B gene (DNMT3B; ICF1), Zinc-finger and BTB domain-containing 24 gene (ZBTB24; ICF2), cell division cycle associated 7 gene (CDCA7; ICF3) and helicase lymphoid specific gene (HELLS; ICF4)." (PMID 39167297, 2024). "Hence, we propose that hypomethylation due to inefficient DNMT1/UHRF1 recruitment at pericentromeric repeats by defects in the CDCA7/HELLS complex could induce pericentromeric instability, which may explain a part of the molecular pathogenesis of ICF syndrome." (PMID 33082427, 2020). "Although the relationships of ZBTB24, CDCA7, and HELLS with DNA methylation are not completely understood, the similarities between ICF syndrome types indicate a possible role for the different genes in the same molecular pathway." (PMID 31963661, 2020).
Immunodeficiency (11 papers, 2015 to 2025). Failure of the immune system to protect the body adequately from infection, due to the absence or insufficiency of some component process or substance. "Mutations of the SNF2 family ATPase HELLS and its activator CDCA7 cause immunodeficiency, centromeric instability, and facial anomalies syndrome, characterized by DNA hypomethylation at heterochromatin." (PMID 39178260, 2024). "Another study discovered a role for CDCA7 in Centromeric Instability and Facial Anomalies syndrome, a life-threatening immunodeficiency." (PMID 32716971, 2020). "Immunodeficiency, centromeric instability, and facial anomalies syndrome (ICF) is a rare genetic defect that is inherited in an autosomal recessive manner, and the pathogenic genes include DNMT3B, ZBTB24, CDCA7, and HELLS." (PMID 39958354, 2025). "Immunodeficiency, centromeric instability, facial anomalies (ICF) syndrome is a rare autosomal recessive disorder that is caused by mutations in either DNMT3B, ZBTB24, CDCA7, HELLS, or yet unidentified gene(s)." (PMID 33082427, 2020). "In addition, recent studies have highlighted a role for ZBTB24, CDCA7 and HELLS in Non-homologous end joining (NHEJ), a pathway involved in DNA repair but also in immunoglobulin class-switch recombination, linking LoF of ICF factors to immunodeficiency that affects most of ICF patients." (PMID 33916664, 2021).
breast carcinoma (10 papers, 2013 to 2026). "The frequency of rs1550623-A located in the intron region of CDCA7 was fixed at 1 in HM people and other East Asians, and this variant was reported to be the strongest risk allele for breast cancer in Europeans (0.8469)." (PMID 38273256, 2024). "The co-expression profile showed that CENPW had the highest association coefficient with CDCA7 among 129 breast carcinoma samples in the LU Breast dataset." (PMID 35783290, 2022). "The CENPW expression was positively linked to the transcription level of CDCA7 in a 50-gene qPCR assay (PAM50) for breast carcinoma subtypes." (PMID 35783290, 2022). "CDCA7 (cell division cycle associated 7), was found to be elevated in various types of human cancer, including colon, lung, prostate and breast cancers, suggesting that this protein might play an important role in the development of cancer." (PMID 35167614, 2022). "Overexpression of CDCA7 in breast cancer cells significantly enhanced autophagy-related biological processes and molecular functions." (PMID 41890763, 2026). "Using transmission electron microscopy and mRFP/mCherry-GFP-LC3B tandem fluorescent tagging, we observed that CDCA7 knockdown significantly reduced the number of autolysosomes in breast cancer DTP cells and markedly inhibited autophagic flux." (PMID 41890763, 2026). "According to the outcome of the GEPIA database survival analysis, CDCA7 upregulation was correlated with poorer OS in breast carcinoma patients, which was consistent with the effect of CENPW on breast cancer." (PMID 35783290, 2022). "Next, we discovered that the genes interacting with CENPW are mainly concentrated in the cell cycle pathway, and CENPW is co-expressed with CDCA7, which is also highly expressed in breast carcinoma and leads to a worse prognosis." (PMID 35783290, 2022). "Further investigation reveals that CDCA7 expression is also up-regulated in breast carcinoma and leads to poor prognosis." (PMID 35783290, 2022). "Previous reports showed that overexpression of CDCA7 predicts poor prognosis and tumor progression in human breast cancer, lung adenocarcinoma and lymphoma, colorectal cancer, and pancreatic diseases." (PMID 34737951, 2021). "The CDCA7 mRNA was overexpressed in the TNBC subtype of breast cancer by more than 1.5 - fold relative to normal control sample." (PMID 29467944, 2018). "It was reported that CDCA7 was aberrantly expressed in both solid tumors and hematological tumors, including lung cancer, stomach cancer, breast cancer, colorectal cancer, lymphoma, acute myelogenous leukemia and so on, suggesting its essential role in promoting tumorigenesis." (PMID 33648519, 2021). "In addition, we analyzed the immune process of CDCA7 in the breast cancer microenvironment, and the expression level of CDCA7 was negatively correlated with macrophages, positively correlated with immune invasion of B cells, neutrophil, dendritic cell, which is consistent with the results of CENPW." (PMID 35783290, 2022). "As reported, CDCA7 was markedly upregulated in TNBC, the most aggressive subtype of breast cancer, related to tumor proliferation and metastatic relapse status, and predicted poor prognosis." (PMID 33648519, 2021). "The purpose of the present study was to investigate the prognostic value of the candidate biomarkers CCNB2, ASPM, CDCA7, KIAA0101, and SLC27A2 in breast cancer." (PMID 23282137, 2013). "Here, we present a validation of the prognostic role of five selected candidate biomarkers (CCNB2, ASPM, KIAA0101, CDCA7, and SLC27A2) included in these gene signatures using an independent breast cancer cohort." (PMID 23282137, 2013).
colorectal cancer (8 papers, 2020 to 2024). A primary or metastatic malignant neoplasm that affects the colon or rectum. "The lncRNA FGD5-AS1/miR-302e/CDCA7 axis aggravates cell proliferation, migration, and invasion in colorectal cancer." (PMID 38955795, 2024). "lncRNA FGD5-AS1 promoted colorectal cancer cell proliferation, migration, and invasion through upregulating CDCA7 via sponging miR-302e." (PMID 36595551, 2023). "FGD5-AS1 has been shown to promote colorectal cancer cell proliferation, migration, and invasion by functioning as a sponge for miR-302e and regulating CDCA7 expression." (PMID 34095215, 2021). "As a family member of the cell division cycle proteins, CDCA7 was markedly overexpressed in colorectal cancer and lung adenocarcinoma." (PMID 33384961, 2020). "In addition, studies on CDCA7 have found that its high expression can help to predict poor prognosis and tumor progression in colorectal carcinoma and kidney carcinoma." (PMID 35783290, 2022). "However, it is worth noting that in other types of human cancers, FGD5-AS1 was shown to exert its oncogenic modulation through other ceRNAs, such as miR-302e/CDCA7 axis in colorectal cancer or hsa-miR-107/FGFRL1 in lung cancer." (PMID 32849774, 2020). "besides, colorectal cancer patients with low expression of CDCA7 had better overall survival." (PMID 33384961, 2020).
lymphoma (8 papers, 2020 to 2025). A malignant (clonal) proliferation of B- lymphocytes or T- lymphocytes which involves the lymph nodes, bone marrow and/or extranodal sites. "Firstly, GPX4 blocks the cell cycle's S-phase and inhibits lymphocyte proliferation, while also inhibiting the expression of 16 key upregulated pathogenic genes in inhibiting CDCA7 gene's expression significantly and lymphoma." (PMID 38333875, 2024). "CDCA7 is frequently overexpressed in human cancers, including a large variety of B- and T-cell leukemias and lymphomas, and its loss has been shown to reduce T- and B-lymphomagenesis in vivo." (PMID 32872487, 2020). "Studies have demonstrated that CDCA7 knockdown limits the migration of cancer cells by regulating tubulin and actomyosin cytoskeleton dynamics in lymphoma." (PMID 34082692, 2022). "CDCA7 also contributes to anchorage-independent growth, and silencing CDCA7 impaired lymphoma cell migration and invasion in in vitro and in vivo models." (PMID 32872487, 2020). "Literature reports suggest that CDCA7 plays an important role in lymphoma." (PMID 38333875, 2024). "And CDCA7 was essential for invasion and migration of lymphoma cells." (PMID 33648519, 2021). "However, literature has reported that CDCA7 plays a crucial role in the pathogenesis of lymphoma." (PMID 38333875, 2024). "CDCA7 stabilizes MYC protein through AKT-mediated phosphorylation, thereby inhibiting the expression of pro-apoptotic factors such as Bim and promoting lymphoma cell transformation." (PMID 41189944, 2025). "Indeed, our previous findings revealed that silencing CDCA7, a gene overexpressed in lymphoid tumors, specifically inhibited cell growth in 3D gels, without inhibiting proliferation in 2D conditions, and reduced lymphoma growth in vivo and tumor cell migration and invasion." (PMID 39068166, 2024).
lung adenocarcinoma (6 papers, 2020 to 2025). A carcinoma that arises from the lung and is characterized by the presence of malignant glandular epithelial cells. "Increased CDCA7 expression is observed in lung adenocarcinoma compared to adjacent normal tissues and enhances cell proliferation via accelerating cell cycle." (PMID 40630134, 2025). "One research in lung adenocarcinoma reported that CDCA7 promoted lung adenocarcinoma proliferation through regulating the cell cycle, while its mechanism has not been completely elucidated yet." (PMID 34737951, 2021). "CDCA7 enhance cell proliferation in lung adenocarcinoma by mediating G1 phase and regulating apoptosis." (PMID 33384961, 2020). "For CDCA7, the fold changes displayed in Hou's dataset were 5.997, 9.075, and 7.392 in lung adenocarcinoma, SCC, and large-cell LC, respectively." (PMID 32104702, 2020). "Wang etc. discovered that CDCA7 was preferentially elevated in lung adenocarcinoma (LUAD) and overexpression of CDCA7 could enhance cell proliferation in LUAD through G1 phase promotion." (PMID 33648519, 2021).
lung carcinoma (5 papers, 2013 to 2025). "Compared with normal tissues, CDCA7 is overexpressed in ovarian, colorectal, breast, and lung cancer tissues." (PMID 40732340, 2025). "CDCA7 is frequently overexpressed in human cancers such as chronic myelogenous leukemia and lung cancers." (PMID 23874428, 2013). "The CDCA7 and KIAA1432 genes have been reported to be highly overexpressed in lung cancer cells." (PMID 28355295, 2017).